IGF2 (insulin like growth factor 2)
Diseases named in the same sentence as IGF2 in open-access papers (continued):
Sharing a sentence is not in itself a finding about the gene and the disease.
Insulin resistance (51 papers, 2007 to 2025). Increased resistance towards insulin, that is, diminished effectiveness of insulin in reducing blood glucose levels. "In humans, an IGF2 polymorphism causes the insulin resistance and hyperandrogenism in PCOS patients." (PMID 26046837, 2015). "In Silver Russell syndrome Igf2/H19 hypomethylation is associated with insulin resistance and a phenotype of impaired fasting glucose in the presence of low BMI." (PMID 26237614, 2014). "The fact that PCOS can be linked to genomic variants such as the serum antioxidant enzyme paraxonase and variant IGF2 genes emphasizes the likelihood that multifactorial environmental factors contribute to the final insulin resistance phenotype." (PMID 21209881, 2010). "Studies have observed associations between elevated IGF2 expression and insulin resistance in specific tissues, suggesting that altered IGF2 signaling could play a role in the etiology of type 2 diabetes and related metabolic disorders." (PMID 40566344, 2025). "Following transportation into the liver via the enterohepatic circulation, SCFA may be related to the decreasing Igf2, associated with insulin resistance and lipid metabolism disorder." (PMID 33746902, 2021). "Further studies are needed to confirm whether growth restriction in association with premature pubarche and insulin resistance is a specific manifestation of reduced IGF2 expression." (PMID 22646060, 2012). "Based on our observation from this study, we hypothesise that in addition to affecting pre- and post- natal growth, IGF2 in humans may have a causal role in timing of pubarche and insulin resistance." (PMID 22646060, 2012). "Further studies are needed to confirm whether growth restriction in association with premature pubarche and insulin resistance is a specific manifestation of loss of IGF2 expression through IGF2/H19 loss of methylation." (PMID 22646060, 2012). "Transcriptome analysis also suggests decreased insulin secretion and increased insulin resistance in pregnant Tibetans, which is triggered, among other things, by a significantly lower expression of placenta-specific insulin-like growth factor 2 (IGF2)." (PMID 40003440, 2025). "Group-based comparisons of circulating growth factors and insulin resistance markers revealed statistically significant differences in IGF-2 (p < 0.001), HOMA-IR (p < 0.001), insulin (p = 0.0025), and glucose concentrations (p < 0.001)." (PMID 40943286, 2025). "Variants within this cluster mapped to genes with known effects on insulin resistance, including IGF2, INSR, KLF14, and PPARG in adipose tissue." (PMID 38200577, 2024). "A previous paper indicated that male offspring of GDM mice have lower expression of IGF2 in the liver, and they show more severe glucose intolerance and insulin resistance than female offspring." (PMID 37152930, 2023). "have reported a case of a patient harboring an Igf2 defect combined with insulin resistance and lipid metabolism disorders." (PMID 33746902, 2021). "IGF2 plays a key role in glucose metabolism, HSPB6 is associated with insulin resistance, and MCF2L2 is related to type 1 diabetes and polycystic ovary syndrome." (PMID 34645493, 2021). "Another study which showed a similar alteration in the Igf2/H19 ICR upon maternal low-protein diet also illustrated insulin resistance and increased adipose expansion in offspring, implicating modifications in Igf2/H19 methylation in adipose growth." (PMID 32494846, 2020). "Both insulin resistance and IGF2 affect energy metabolism, cell differentiation and proliferation, and suppression of apoptosis." (PMID 30200454, 2018). "Peripheral insulin resistance augments IGF1 levels, and loss of imprinting (LOI) of the IGF2 gene is associated with poor survival in CRC." (PMID 27409167, 2016).
Insulin resistance (continued). "Furthermore, insulin resistance and glucose intolerance in male offspring born of GDM pregnancies have been linked to DNA hypermethylation-related downregulation of H19, as well as IGF2, which originate from the same imprinted locus." (PMID 39765830, 2024). "IGF2 plays a key role in glucose metabolism, HSPB6 might be associated with insulin resistance, and MCF2L2 might be one of the most important marker genes contributing to type 1 diabetes and polycystic ovary syndrome." (PMID 34645493, 2021). "Recently a woman with intrauterine growth retardation, short stature, lactation failure, and insulin resistance with altered fat distribution was found to have a balanced translocation that disrupted the paternally-derived Insulin-like Growth Factor 2 (IGF2) gene." (PMID 19216786, 2009). "A statistically significant positive correlation between the value of the indicator HOMA-IR and the concentration of IGF-2 in umbilical cord blood of newborns delivered by women suffering from GDM may suggest a potential role of IGF-2 in the development of insulin resistance in utero." (PMID 33053704, 2020). "Our case of growth restriction, premature pubarche and insulin resistance in the absence of body asymmetry or other features of SRS adds to the expanding phenotype of IGF2/H19 methylation abnormalities." (PMID 22646060, 2012). "We hypothesised that severe pre- and post-natal growth restriction associated with insulin resistance and precocious pubarche in the absence of SRS are also caused by downregulation of IGF2 through hypomethylation, gene mutation or structural chromosomal abnormalities." (PMID 22646060, 2012). "We have previously reported that severe pre- and post-natal growth restriction associated with insulin resistance and precocious pubarche in a woman without body asymmetry or other SRS features resulted from a balanced translocation affecting the regulation of her IGF2 gene expression." (PMID 22646060, 2012).
type 2 diabetes (42 papers, 2009 to 2025). "The imprinted Igf2 (insulin-like growth factor 2) gene is highly transcribed during early life and has been identified in recent genome-wide association studies as a type 2 diabetes susceptibility gene in humans." (PMID 33833312, 2021). "Furthermore, the results of the present study is consistent with previous reports of the involvement of genomic imprinting in the association between class III allele and type 2 diabetes and also the fact that IGF2 gene is a representative maternal imprinting gene." (PMID 23818790, 2009). "The involvement and change of gene expression of CACNA1G, IGF2, MLH1, and SOCS1, in addition to causing CRC, can cause diseases such as type 2 diabetes, Fanconi’s anemia, and toxoplasmosis." (PMID 38874740, 2024). "Reciprocal regulation IGF2AS and IGF2 is critical in modulating angiogenic development in myocardial tissues in type 2 diabetes." (PMID 29867565, 2018). "The IGF2-INS-TH region on human chromosome 11p15.5 has been associated with various common disorders including the metabolic syndrome, type 2 diabetes and coronary heart disease." (PMID 23818790, 2009). "For example, prenatal factors such as mode of conception and maternal diet have been found to affect the DNA methylation of several type 2 diabetes-related genes, notably the insulin-like growth factor II (IGF2) in children that are prenatally exposed to famine conditions." (PMID 35409335, 2022). "Differential methylation of IGF2, as well as other type 2 diabetes-related genes, have been found in children born to mothers experiencing famine, further pointing to epigenetics as a mechanism connecting prenatal nutrition and the onset of type 2 diabetes later in life." (PMID 29026446, 2017). "However, a more recent meta-analysis of GWAS for type 2 diabetes studies in African Americans has found a novel type 2 DM locus near the insulin and IGF2 genes." (PMID 25922844, 2015). "IGF-2 mRNA binding proteins (IMPs) is a family of three closely related proteins (IMP1, IMP2, and IMP3) which bind IGF-2 mRNA and implicated in susceptibility to type 2 diabetes." (PMID 24051403, 2013). "More data are needed to indicate whether IGF2 methylation patterns can be causal for VLBW subjects’ higher levels of risk factors of cardiovascular disease and type 2 diabetes." (PMID 23840686, 2013). "In this study, we used ‘real-world’ data to examine the hypothesis that concentrations of IGF2 and IGFBP2 at baseline were associated with longitudinal trends in glomerular filtration rate (GFR) in type 2 diabetes." (PMID 23781310, 2012). "IGFBP2 and IGF2 measurements were performed in 436 individuals (263 males) with type 2 diabetes." (PMID 23781310, 2012). "The insulin-like growth factor 2 (IGF2) mRNA-binding proteins (IGF2BP1-3 or IMP1-3) are a family of RNA binding proteins that participate in post-transcriptional gene regulation; notably, SNPs in the second intron of the human IMP2 gene are associated with increased risk for Type 2 Diabetes." (PMID 28753127, 2017). "The OR estimate for type 2 diabetes did not change after exclusion of three SNPs in the IGFBP3 or IGF2 gene regions." (PMID 32548700, 2020). "FOS, IGF1R, IGF2, FOXO1, and NTF3 might target “TGF-β signaling pathway”, “the hedgehog signaling pathway”, “retinol metabolism”, or “type II diabetes mellitus” pathways respectively." (PMID 32694937, 2020). "In addition, plasma levels of insulin-like growth factor-2 (IGF-2) are increased in obese and type 2 diabetic patients." (PMID 25052889, 2014). "It is possible that an increase in IGFBP2 concentrations occurs in type 2 diabetes followed by an increase in local IGF1 and IGF2 concentrations in the renal glomerulus, very similar to the hypothesis postulated for IGF1 and IGFBP1 interaction in nephropathy." (PMID 23781310, 2012). "We therefore tested the hypothesis that circulating levels of IGF2 and IGFBP2 predict longitudinal renal function in individuals with type 2 diabetes." (PMID 23781310, 2012).
type 2 diabetes (continued). "Based on the ceRNA network, we also discovered that FOS, IGF1R, IGF2, FOXO1, and NTF3 might target the “TGF-β signaling pathway”, “the hedgehog signaling pathway”, “retinol metabolism”, or “type II diabetes mellitus” pathways respectively, thereby modulating the subsequent development of ICC." (PMID 32694937, 2020). "As far as we know, two previous studies in humans, with small sample size (n = 39–40), examined protein or gene expression of the IGF1, IGF2, IGFBP3, INSR, IGF1R and downstream targets IRS1, IRS2 and mTOR in women with or without type 2 diabetes." (PMID 29486734, 2018).
rhabdomyosarcoma (36 papers, 1995 to 2025). A rare aggressive malignant mesenchymal neoplasm arising from skeletal muscle. "Any condition resulting in biallelic expression, including paternal uniparental disomy and loss of imprinting, brings about IGF2 mRNA overexpression associated with increased risk of WT, hepatoblastoma, rhabdomyosarcoma, and neuroblastoma." (PMID 36284226, 2022). "Mechanistically, IGF2 is overexpressed in both subtypes of rhabdomyosarcoma due to loss of imprinting or heterozygosity at the 11p15.5 locus." (PMID 34440844, 2021). "A well known growth factor circuit implicated in the genesis of human rhabdomyosarcoma is based on coexpression of IGF2 and its receptor IGF1R, a feature shared also by the rhabdomyosarcoma of BALB-p53Neu mice." (PMID 24334679, 2014). "Loss of alleles and imprinting at 11p15.5 together with disruption of genes such as IGF2 have also been implicated in rhabdomyosarcoma development." (PMID 24455040, 2012). "Activation of IGF2 seems to be a feature of all rhabdomyosarcomas, even though 11p15.5 loss of heterozygosity and IGF2 loss of imprinting are alterations predominantly associated with the embryonal and alveolar subtypes, respectively." (PMID 24455040, 2012). "IGF2-targeted siRNA cause a decreased in vitro growth of rhabdomyosarcoma." (PMID 30732578, 2019). "In rapidly growing human rhabdomyosarcoma (RD) cells, the IGF2 mRNA designated leader 4 (L4) is constitutively translated, whereas the IGF2 mRNA designated leader 3 (L3) is translated in a rapamycin-inhibitable manner, through an IRES-mediated mechanism." (PMID 40940829, 2025). "The interruption of IGFs autocrine rhabdomyosarcoma circuits through passive or active immune neutralization of IGF2 has been recently investigated in a preclinical setting." (PMID 34440844, 2021). "BALB-p53Neu male mice, injected to generate IGF2-dependent rhabdomyosarcoma, were treated with anti-IGFs antibodies and the results indicated a significant delay in the sarcoma onset and prolonged overall survival." (PMID 34440844, 2021). "The induction of IGF2 is also partially involved in the proliferation and survival of rhabdomyosarcoma cells." (PMID 32694937, 2020). "We showed here for the first time that immune targeting of the autocrine IGF2 delayed IGF1R-dependent rhabdomyosarcoma genesis." (PMID 30732578, 2019). "We therefore studied the possibility to hamper rhabdomyosarcoma growth with passive and active immune approaches targeting IGF2." (PMID 30732578, 2019). "The receptor tyrosine kinase, IGF2 is another potential target, given that either loss of imprinting or PAX-FOXO1-driven gene expression can induce the overexpression of IGF2 in rhabdomyosarcoma tumors." (PMID 31921698, 2019). "To verify the IGF2 dependence of such murine rhabdomyosarcoma model, we obtained a rhabdomyosarcoma cell line (RMSp53Neu-5) and we treated it in vitro with NVP-AEW541, a small molecule inhibitor of IGF1R, or with specific siRNAs." (PMID 30732578, 2019). "Insulin-like growth factor 2 mRNA-binding proteins (IGF2BPs), first identified in the human rhabdomyosarcoma cell line, interact with the human IGF-II leader-3 mRNA and regulate its translation." (PMID 31658691, 2019). "These mice develop almost simultaneously IGF2-dependent rhabdomyosarcoma and IGF2-independent salivary carcinoma, thus allowing to evaluate the specificity of anti-IGFs treatment." (PMID 30732578, 2019). "Vaccinated mice received the intravenous injection of rhabdomyosarcoma cells to study the effects of anti-IGF2 antibodies against developing metastases." (PMID 30732578, 2019). "In this paper we investigated passive or active immune neutralization of IGF2 to interrupt IGF2-based autocrine circuits in experimental models of rhabdomyosarcoma." (PMID 30732578, 2019). "Insulin-like Growth Factor Receptor-1 (IGF1R) system sustains the genesis of rhabdomyosarcoma through IGF2 autocrine overexpression." (PMID 30732578, 2019).
rhabdomyosarcoma (continued). "Mice with anti-IGF2 antibodies were partially protected against the metastatic growth of IGF2-addicted rhabdomyosarcoma cells." (PMID 30732578, 2019). "Mice with autochthonously produced anti-IGF2 antibodies were partially protected from an intravenous challenge with IGF2-overexpressing murine rhabdomyosarcoma cells." (PMID 30732578, 2019). "In this paper we investigated the possibility to exploit immunity to interrupt the IGF2-autocrine system involved in the genesis and growth of rhabdomyosarcoma." (PMID 30732578, 2019). "Igf2 is known to drive an autocrine circuit in human and mouse rhabdomyosarcoma, hence its overexpression prior to tumor development supported the validity of this screening approach." (PMID 24334679, 2014). "In order to determine whether we could exploit this splicing process as a therapeutic vulnerability and target the IGF-2 pathway in rhabdomyosarcoma, we employed SSO technology." (PMID 35017650, 2022). "Furthermore, with the exception of fusion-positive alveolar rhabdomyosarcomas, IGF2 expression in DSRCT is significantly higher than in other fusion positive sarcomas." (PMID 32703985, 2020). "Rhabdomyosarcoma is an IGF2-dependent tumor, due to the autocrine overexpression of IGF2." (PMID 30732578, 2019). "Immune targeting of autocrine IGF2 inhibited rhabdomyosarcoma genesis and metastatic growth." (PMID 30732578, 2019). "IGF2 is a new target which could be neutralized by immune approaches in prevention and therapy of rhabdomyosarcoma." (PMID 30732578, 2019). "Since IGF2 is involved both in etiogenesis and in growth of rhabdomyosarcoma, the interruption of this autocrine circuit could have both preventive and therapeutic effects." (PMID 30732578, 2019). "IGF2BP3 protein could bind to IGF2 mRNA and promote IGF2 protein expression in human rhabdomyosarcoma cells." (PMID 26327240, 2015). "Consistent with this hypothesis, Igf2 has been shown to be downstream of Hedgehog signalling in pluripotent mesenchymal cells as well as in medulloblastomas and rhabdomyosarcomas." (PMID 22952916, 2012). "Microarray analysis demonstrated that IGF2 and IGF1R are both highly expressed in rhabdomyosarcoma cell lines, xenografts, and human tumor samples." (PMID 34440844, 2021). "Overall, IGF2 and IGF1R constitute a potent autocrine signalling axis, which promotes proliferation of rhabdomyosarcoma tumors." (PMID 34440844, 2021). "The immune targeting of IGF2 can hamper both the onset and the metastatic growth of IGF1R-addicted rhabdomyosarcoma." (PMID 30732578, 2019). "In RD rhabdomyosarcoma cells, the concurrent dual phosphorylation of IMP2 Ser162 and Ser164 is inhibited by rapamycin coincident with inhibition of IMP2 binding to the IGF2 leader 3 5’UTR and IGF2 leader 3 mRNA translation by internal ribosomal entry." (PMID 28753127, 2017). "Both IGF1 and IGF2 act through the tyrosine kinase insulin-like factor 1 receptor (IGF1R), which is widely overexpressed in multiple childhood sarcomas, including rhabdomyosarcomas, and other cancers such as breast cancer, prostate cancer and lung cancer." (PMID 28793874, 2017). "In rhabdomyosarcoma, PLAG1 was shown to upregulate insulin-like growth factor 2 (Igf2), a known target gene, alter alpha serine/threonine kinase (AKT) and mitogen-activated protein kinase (MAPK) pathways and positively regulate proliferation and survival of rhabdomyosarcoma cells." (PMID 38240991, 2024). "A subset (MEST, PLAGL1, PEG3, DLK1, IGF2) showed elevated expression in various embryonal cancers, especially rhabdomyosarcoma, as compared to non-embryonal cancers and normal tissues." (PMID 36437415, 2023). "While several IGF1R-targeted strategies have been investigated to interphere with rhabdomyosarcoma growth, no attempt to neutralize IGF2 has been reported." (PMID 30732578, 2019). "Passive administration of antibodies neutralizing IGFs delayed the onset of IGF2-overexpressing rhabdomyosarcoma but not of IGF2-independent salivary carcinoma." (PMID 30732578, 2019).
rhabdomyosarcoma (continued). "The interruption of IGFs autocrine rhabdomyosarcoma circuits targeting IGF2 through neutralizing antibodies was not studied so far." (PMID 30732578, 2019). "Furthermore, IGF2, the potent ligand of IGF1R, is also overproduced in rhabdomyosarcomas." (PMID 28793874, 2017). "We previously found that rhabdomyosarcomas, but not salivary gland carcinomas, overexpressed IGF2 concomitant to membrane IGF1R, thus suggesting that, like the human counterpart, experimental rhabdomyosarcoma could harbor an autocrine IGF circuit." (PMID 30732578, 2019).